RN7SL632P (RNA, 7SL, cytoplasmic 632, pseudogene)
Gene: Miscellaneous RNA gene on chromosome 2 (60,831,664 to 60,831,929, reverse strand). Ensembl gene ENSG00000241524.
Homologues: Orthologues: chimpanzee Metazoa_SRP (94% identical), guinea pig Metazoa_SRP (67% identical), macaque Metazoa_SRP (59% identical), rabbit Metazoa_SRP (39% identical). Paralogues in human: RN7SL3 (76% identical), RN7SL1 (76% identical), RN7SL2 (74% identical), RN7SL566P (74% identical), RN7SL126P (73% identical), RN7SL357P (73% identical), RN7SL230P (73% identical), RN7SL518P (73% identical), RN7SL546P (73% identical), RN7SL664P (73% identical), RN7SL717P (73% identical), RN7SL797P (73% identical), and 706 more.